FOXC1 (forkhead box C1)
Diseases named in the same sentence as FOXC1 in open-access papers (continued):
Sharing a sentence is not in itself a finding about the gene and the disease.
tumor (continued). "After FOXCUT and FOXC1 (an EMT-related gene) silencing, the expression levels of MMP2, MMP7, MMP9, and VEGF-A were downregulated, suggesting a possible role for the FOXC1/FOXCUT gene pair in tumor angiogenesis in OSCC." (PMID 41020820, 2025). "One possibility is that FOXC1/FOXC2 loss results in tumour dedifferentiation, producing a more aggressive and plastic tumour phenotype." (PMID 40683913, 2025). "Specifically, MYOC, TBK1, COL1A1, and COL1A2 were upregulated in tumor tissues, while FOXC1, LRP2, and TEK was downregulated (all p < 0.05)." (PMID 40808675, 2025). "In clinical NB cases, higher OGT, FOXC1, ASNS, GPT2, CBS, or FTH1 levels are correlated with worse survival, while lower ecircOGT or OGT-570aa expression is associated with tumor progression." (PMID 40416363, 2025). "As a part of the FOX transcription factor family, FOXC1 functions in embryonic development and tumor progression." (PMID 40421012, 2025). "As a transcription factor, FOXC1 promotes tumor invasion or metastasis by increasing the expression of neural precursor cell expressed developmentally down-regulated 9 (NEDD9) or matrix metalloprotease 7 (MMP7)." (PMID 40416363, 2025). "We next investigated functional interplay of OGT and FOXC1 in asparagine/alanine biogenesis essential for ferroptosis repression and tumor progression." (PMID 40416363, 2025). "Rescue studies were carried out to disclose the contribution of asparagine and alanine to FOXC1-induced tumor growth or aggressiveness." (PMID 40416363, 2025). "Our results indicate that stromal FOXC1 and tumor pERK1‐2 expression provide stronger prognostic value compared to established factors, including cell of origin and MYC/BCL2 double expression." (PMID 39404228, 2024). "FOXC1 induced EMT reported in epithelial tumor cells and suppression of FOXC1 can partially reverse the EMT process." (PMID 38318192, 2024). "Stromal FOXC1 and tumor pERK1‐2 were determinants of DLBCL prognosis, whose addition significantly improved prognostic performance of the NCCN‐IPI." (PMID 39404228, 2024). "We computed every combination of prognostic factors including established factors, stromal FOXC1 and tumor pERK1‐2‐to calculate the C‐index." (PMID 39404228, 2024). "From the present study, we noted that high levels of FOXC1‐positive stromal cells and high pERK1‐2‐positive tumor cells within the tumor microenvironment were significantly related to worse prognosis of DLBCL patients." (PMID 39404228, 2024). "The CCK8 assay and colony formation assay revealed a substantial reduction in the proliferation capability of tumor cells following FOXC1 knockdown." (PMID 38413558, 2024). "FOXC1 stromal cell expression and pERK1‐2 tumor cell expression correlated with a significant decrease in both PFS and OS by log‐rank and multivariable analysis." (PMID 39404228, 2024). "ML models reconfirmed the addition of stromal FOXC1 expression and tumor pERK1‐2 to NCCN‐IPI score had the highest C‐index (0.952) among combinations." (PMID 39404228, 2024). "Analysis by ML models and methods confirmed the findings that the addition of both stromal FOXC1 and tumor pERK1‐2 to established factors of prognosis (NCCN‐IPI, cell of origin, and MYC/BCL2 double expression) improved C‐index." (PMID 39404228, 2024). "Compared with matched adjacent adjacent tissues, FOXC1 protein expression was lower in 5 pairs of tumor tissues." (PMID 39093497, 2024). "The addition of stromal FOXC1 and tumor pERK1‐2 to the NCCN‐IPI score significantly improved prediction of time to death compared with NCCN‐IPI score alone (Harrell's C‐index = 0.801 vs. 0.764; p = 0.030)." (PMID 39404228, 2024). "Because FOXC1 is a transcription factor and central hub gene that controls hundreds of gene networks, upregulated FOXC1 expression in cancer has widespread effects on many key biological processes related to tumor growth." (PMID 39430239, 2024).
tumor (continued). "To validate that the USP10-mediated tumor-promoting effects were dependent on FOXC1, we conducted a series of functional experiments." (PMID 39430239, 2024). "As expected, the panel of 81 genes repressed by FOXC1 was seen to have significantly lower expression in tumor and metastatic breast invasive carcinoma samples, inclusive of all subtypes." (PMID 39171293, 2024). "Through the CCK8 assay and apoptosis assay, we observed heightened sensitivity of tumor cells to cisplatin following FOXC1 knockdown." (PMID 38413558, 2024). "On DLBCL patient tissue, FOXC1 expression was preferentially observed in the cytoplasm of star‐shaped stromal cells within the tumor microenvironment and rarely in tumor cells; pERK1‐2 expression was counted in the DLBCL tumor cell nucleus." (PMID 39404228, 2024). "Future work will focus on validating the core targets and the biological processes these targets are involved in, as well as expanding FOXC1’s role to patient tumor samples that are more complex and heterogeneous compared to cell lines using single-cell omics." (PMID 39171293, 2024). "We demonstrate substantial improvements by incorporating markers of the tumor microenvironment, specifically stromal FOXC1 and tumor pERK1‐2 expressions, offering a multidimensional approach to DLBCL prognosis." (PMID 39404228, 2024). "Multidimensional analysis using statistics and machine learning (ML) models assessed prognostic value of established clinicopathologic variables with stromal FOXC1 and tumor pERK1‐2 expressions." (PMID 39404228, 2024). "Incorporating both stromal FOXC1 and tumor pERK1‐2 expressions markedly improved the prognostic accuracy of the NCCN‐IPI, as evidenced by both classical statistics and ML models." (PMID 39404228, 2024). "The Forkhead box C1 (FOXC1) transcription factor participates in various biological processes in both normal and tumor cells." (PMID 39430239, 2024). "Subsequent measurements and analyses of the weight and volume of each tumor indicated that the FOXC1-knockout group exhibited significantly lower tumor volume and weight compared to the control group." (PMID 38413558, 2024). "The addition of both stromal FOXC1 and tumor pERK1‐2 to NCCN‐IPI significantly improved C‐index than NCCN‐IPI alone in the prediction of time to death, (0.801 vs. 0.764, p = 0.030)." (PMID 39404228, 2024). "All indices of C‐index improved from the addition of both stromal FOXC1 and tumor pERK1‐2 to established factors of prognosis; average C‐index of ML improved from 0.807 to 0.841 and the maximum C‐index from 0.921 to 0.939." (PMID 39404228, 2024). "Further experiments demonstrated that FOXC1 acted as a tumor suppressor to regulating AMPK/mTOR pathway." (PMID 39093497, 2024). "In this study, we focused on a new binding protein, FOXC1, which is also a reported oncogene in many tumor types." (PMID 39430239, 2024). "In general, our study demonstrates that FOXC1 exerts its tumor suppressor role by promoting ABHD5 transcription to regulating AMPK/mTOR signal pathway." (PMID 39093497, 2024). "Together these findings reveal a new molecular connection between FOXC1 and tumor immunosuppression, presenting another conceptual framework for better understanding and exploiting of patient‐specific responses to cancer immunotherapy." (PMID 38107056, 2023). "TIMP1, PGF, FSTL3, SNAI1, and FOXC1 were highly expressed in CAFs with high stemness scores in the tumor intestinal tissues." (PMID 37017587, 2023). "FOXC1 suppression induces ER-α expression in BC cells, which helps in increased estrogen uptake, resulting in the growth and proliferation of tumor cells." (PMID 37900178, 2023). "In vitro findings lend credence to the potential tumor suppressor activity of FOXC1, particularly in its impact on cell proliferation." (PMID 37849766, 2023). "c-Myc is a downstream target of FOXC1 in several cancer types and is important for tumor progression." (PMID 35096062, 2022).
tumor (continued). "Consistently, in vivo data also showed that the knockdown of FOXC1 significantly inhibited tumor growth." (PMID 35096062, 2022). "In particular, all tumor subtypes exhibited hypomethylation affecting the promoter of the transcription factor FOXC1 and its upstream lncRNA transcript FOXCUT." (PMID 35769412, 2022). "Expression of tumor-related FOXC1 transcription factor increased transiently as early as 4 h after ROS-overproduction in the initial stage of differentiation." (PMID 35365611, 2022). "FOXC1 promoted HCC tumor metastasis via transactivating Snail, a central transcription factor regulating a bundle of metastasis-related genes." (PMID 35255005, 2022). "As an important member of the forkhead box Fox family, FOXC1 plays important roles in human congenital and tumor diseases." (PMID 35504885, 2022). "Tumor growth was promoted by treatment of immune cells with FOXC1 H446HG overexpressing lentivirus compared with the wild type." (PMID 35504885, 2022). "In vivo tumorigenicity assays suggested that down-regulated DNMT3B significantly inhibited tumor growth induced by Huh7-FOXC1 cells, whereas upregulation of DNMT3B salvaged the suppression tumor growth induced by FOXC1 knockdown." (PMID 33522955, 2021). "Upregulated FOXC1 in tumor cells induces production and release of cytokines, chemokines and growth factors which mediates recruitment of stromal cells to the TME." (PMID 34540690, 2021). "Taken together, LINC01929 functioned as a tumor-promoting lncRNA via the miR-137-3p/FOXC1 axis in OSCC, suggesting novel targets for OSCC therapy." (PMID 33968763, 2021). "FOXC1 expression is upregulated in some types of cancer and participates in tumor formation as an oncogene." (PMID 33968763, 2021). "We do note, however, that the tumours in our study as well as human TNBCs express transcriptional regulators of alveologenesis such as Elf5, Sox10, Foxc1 and Cebpb." (PMID 33686070, 2021). "To study the oncogenic functions of FOXC1 in GC, we checked the effect of FOXC1 knockout on tumor growth and found that FOXC1 KO significantly decreased the tumor growth of MKN-45 cells (p < 0.05)." (PMID 33987183, 2021). "Among these upregulated PRC2+-CGI genes, we found many well-defined oncogenes and genes encoding tumor-promoting factors such as MYB, TWIST1, SYK, TEAD4, FOXC1, and FGFR3." (PMID 33931649, 2021). "The chemokine CXCL12 and its cognate receptor CXCR4, a transcriptional target of FOXC1 was shown to play central roles in cancer proliferation, angiogenesis, invasion, tumor microenvironment, as well as drug resistance induced by chemotherapy." (PMID 34540690, 2021). "miR-23b-5p was described as acting as a tumor suppressor in a variety of cancers, most importantly by inhibiting the FOXC1 gene, a known oncogene with important roles in signal transduction and tumor progression." (PMID 34830370, 2021). "Some literature suggested that TF FOXC1 plays an important role in tumor development and metastasis." (PMID 33802957, 2021). "Considered a tumor suppressor, EZH2 plays a role in silencing CDH1, FOXC1, DAB2IP, and TIMP3, events linked to metastatic progression." (PMID 34680307, 2021). "FOXC1 is highly expressed in the heart, kidney and skeletal muscles, and has a role in tumor development, tissue-specific gene expression and embryogenesis." (PMID 34809627, 2021). "In this study, we explored the effects of FoxC1 on tumor-like properties and inflammatory responses of RASFs and the potential underlying mechanisms." (PMID 32373221, 2020). "Collectively, our experimental data demonstrated that LINC00242 knockdown exerted anti-tumor effects in GC by inhibiting malignant cell growth, migration, invasion and angiogenesis through miR-141 target-inhibition of FOXC1." (PMID 32587479, 2020). "Additional primary tumor markers found to associate with BCBM progression by more than one study included Ki67, EGFR, FOXC1 and CK5/6." (PMID 32110283, 2020).
tumor (continued). "Knockdown of BAP18 decreased MYC, CCND1, KCNK5, and FOXC1 mRNA expression in xenograft tumor tissue." (PMID 32986841, 2020). "Although FoxC1 is known as an essential factor in cancer pathology, its regulatory contribution to tumor-like characteristics and its role in the pathological progression of RA have not been thoroughly discussed." (PMID 32373221, 2020). "Consistent with an important role in the hypoxic adaptation of lung tumors, hypoxia-inducible knockdown of FOXC1 blunted tumor growth, angiogenesis and metastasis in vivo." (PMID 30764547, 2019). "Crucially, deregulation of FOXC1 contributes to several of these hallmarks across various tumor settings." (PMID 30764547, 2019). "In line with this, we reveal a mechanism by which FOXC1 is related to chemoresistance and promotes tumor growth via the miR-31-5p/LATS2 pathway." (PMID 31623173, 2019). "Previous reports have shown that FOXC1 regulates many pathways related to organ development and function, and many literature sources have shown that FOXC1 plays a key role in tumor progression and cancer cell proliferation." (PMID 31623173, 2019). "Collectively, the available evidence favors generalized roles for MAPK and PI3K signaling in the induction of FOXC1 expression across cancer types, though the receptors acting upstream of this are likely to be tumor-specific." (PMID 30764547, 2019). "Given that FOXC1 has been observed to upregulate VEGFA under tumor hypoxia, it is again possible these molecules constitute a feed-forward regulation loop promoting angiogenesis." (PMID 30764547, 2019). "We further established how elevated DHA suppressed tumor growth and metastasis through the regulation of miR-138-5p and FOXC1 in vivo." (PMID 31783879, 2019). "The OR-LoVo tumor tissue expressed higher FOXC1 protein level compared with that in LoVo tumor tissue." (PMID 31623173, 2019). "In this mechanism, the upregulated expression of FOXC1 leads to expression of the miR-31-5p transcript, which induces cell proliferation by suppressing the expression of an anti-tumor gene, LATS2." (PMID 31623173, 2019). "To validate the relationship between EZH2 and FOXC1, we first quantified FOXC1 protein levels in 20 Luminal B patient tumour samples via immunofluorescence staining of breast tissue biopsies." (PMID 29959321, 2018). "In particular, the upregulation of miRNA 204 and miRNA 495 was shown to invoke tumour suppression through decreased FOXC1 protein expression." (PMID 29487724, 2018). "We further confirmed Foxc1 upregulation in the epithelial compartment of Ezh2-null tumours by qPCR and immunoblotting." (PMID 29959321, 2018). "FOXC1 knockdown decreased tumor incidence rate, tumor volume and tumor weight, whereas, FOXC1 overexpression had the opposite effects." (PMID 30189871, 2018). "FOXC1 was expressed in 60.7% (516/850) of all samples, in 54.6% (247/452) of early-stage tumor samples, and in 67.5% (269/398) of late-stage tumor samples." (PMID 30564302, 2018). "As indicated in, FOXC1 is associated with BLBC through critical signaling pathways and is directly linked to tumor metastasis and invasion." (PMID 29487724, 2018). "By interrogation of our ChIP-Seq data to identify genes losing H3K27me3 in Ezh2−/− compared to Ezh2+/+ tumours, we confirmed that Foxc1 is directly targeted by Ezh2-mediated H3K27me3." (PMID 29959321, 2018). "This work led to the identification of a Luminal B-specific anti-metastatic transcriptional program centred on the master transcriptional regulator FOXC1, which is silenced in these tumours in an Ezh2-dependent manner." (PMID 29959321, 2018). "FOXC1 was expressed in 60.7% (516/850) of all samples, in 54.6% (247/452) of early-stage (T1-T2) tumor samples, and in 67.5% (269/398) of late-stage (T3-T4) tumor samples." (PMID 30564302, 2018). "This suggests that the downstream targets of FOXC1 in these cancers are tumour suppressive, which agrees with multiple functional studies investigating these genes." (PMID 29959321, 2018).
tumor (continued). "On the other hand, Forkhead Box C1 (FOXC1), another member of the forkhead box transcription factors, is an oncogene controlling tumour cell migration and metastasis and it is inhibited by miR-204." (PMID 30037059, 2018). "Overexpression of FOXC1 was related to poor prognosis of tumor, stage of tumor node metastasis, and lymph node metastasis." (PMID 29552326, 2018). "Univariate analysis identified tumor size and FOXC1 overexpression as significant predictors of DFS." (PMID 28493031, 2017). "Accordingly, miR-204 suppresses tumor cell growth, apoptosis and survival by targeting Mcl-1, Bcl-2 and TrkB, impacted tumor migration, invasion and metastasis by targeting FOXC1 and slug." (PMID 28388577, 2017). "Inhibition of FOXC1 expression reduces cell migration and invasion that is induced by EGF, while inhibition of EGFR lowers FOXC1 expression and abrogates tumor growth in mice." (PMID 28629477, 2017). "In the multivariate analysis by Cox regression, only tumor size and FOXC1 were significant factors related to DFS, whereas common pathological factors [such as age, nodal status, differentiation, and lymphovascular invasion (LVI)] were not." (PMID 28493031, 2017). "FOXC1 association with the BLBC subtype was consistent with prior studies of BLBC demonstrating younger age of onset, higher tumor grade, and increased Ki67%." (PMID 27708239, 2016). "Even more interestingly, we found in the in vivo transplantation experiment that the expression of FOXC1 in the grafted miR-138-5p over-expressing tumor samples was significantly down-regulated." (PMID 25875420, 2015). "In many other malignant tumors, FOXC1 has been demonstrated to be a cancer-related factor involved in tumor progression processes such as cell proliferation and cell migration." (PMID 24889262, 2014). "The Fork head box C1 (FOXC1) gene is overexpressed in multiple malignant tumors and is functionally correlated with tumor progression." (PMID 24889262, 2014). "The real-time PCR results also showed that both the lncRNA-FOXCUT expression and the mRNA FOXC1 expression were significantly elevated in OSCC tumor tissues and OSCC cell lines compared with normal oral cavity tissues and oral keratinocyte cell." (PMID 24889262, 2014). "Phenotypes underlying such clustering patterns showed that CTCs maintained higher expression than all tumor cell lines for FOXC1, KRT18, PTEN, NPTN, TGFß1, KRT8, ZEB2, and CXCR4." (PMID 22586443, 2012). "For FOXC1 significant differences in methylation levels were observed between normal breast tissue and invasive tumours (P < 0.001)." (PMID 20056007, 2010). "In our data set, FOXC1 displayed a significantly increased methylation levels from normal breast tissue to invasive tumours with simultaneously lower FOXC1 gene expression as measured by qRT-PCR." (PMID 20056007, 2010). "In particular, FOXC1 showed a significant increase in the methylation frequency in invasive tumours." (PMID 20056007, 2010). "This regulatory mechanism suggests that targeting FOXC1 or its interaction with LINC01123 could potentially disrupt tumor progression in TNBC." (PMID 40255398, 2025). "Additionally, we discovered that FOXC1 is a transcription factor for VWF which was found significant in promoting tumor growth and angiogenesis." (PMID 39906820, 2025). "Similarly, SLC12A1 is regulated by NFIC, GATA2 and FOXC1, ensures ionic balance and cellular volume, thereby supporting tumor cell survival and aggressive behavior." (PMID 39348357, 2024). "Given their shared characteristics in tumor progression, it is plausible that L1CAM may be associated with FOXC1 in TNBC." (PMID 38183514, 2024). "Despite extensive studies on tumor progression, the regulation of FOXC1 remains poorly understood." (PMID 38183514, 2024).